EGFR (epidermal growth factor receptor)
Diseases named in the same sentence as EGFR in open-access papers (continued):
Sharing a sentence is not in itself a finding about the gene and the disease.
infection (continued). "Organoid-derived astrocytes also exhibit some reactive characteristics in response to infection, with ∼70% of organoid-derived infected cells expressing SYNM and 33% expressing EGFR." (PMID 35858406, 2022). "EGFR signaling inhibits lytic infections and HCMV goes to great lengths to inactivate EGFR, through both transcriptional down-regulation and targeted EGFR degradation." (PMID 35083168, 2021). "Treatment of mice with gefitinib inhibited C. albicans-induced phosphorylation of both EphA2 and EGFR in the oral epithelial cells, and reduced the tissue levels of CXCL1/KC, CCL20, and S100A8 after both 1 and 2 days of infection." (PMID 33471869, 2021). "In contrast to its role during lytic infections, HCMV utilizes EGFR signaling for entry and subsequent trafficking of the viral genome to the nucleus in undifferentiated myeloid lineage cells supporting latent infections." (PMID 35083168, 2021). "As predicted by the in vitro data, treatment with gefitinib reduced the phosphorylation of both EGFR and EphA2 in CD45- EpCam+ cells after 1 d of infection." (PMID 33471869, 2021). "SIV infection was detected by flow cytometry for GFP expression 3 days post-infection and protection assessed by comparing the percentage of GFP+ cells among transduced EGFR+ cells and untransduced EGFR− cells." (PMID 34485613, 2021). "Like infection of monocytes, initial infection of CD34+ HPCs relies on receptor-ligand engagement with EGFR engagement being key to early infection." (PMID 34025614, 2021). "For this review and for infection of monocytes and CD34+ HPCs, gB engagement of EGFR is essential for entry and the post entry events related to nuclear translocation as well as for the associated downstream signaling." (PMID 34025614, 2021). "EGFR and downstream PI3K signaling are also important to mediate infection that leads to establishment of latency in CD34+ cells." (PMID 34831300, 2021). "The authors suggest that EGFR signaling is downregulated by HCMV in the early stages of infection and that EGFR signaling promotes latency later in infection." (PMID 34299120, 2021). "For this, ARPE-19 cells were infected with cell-free HSV-1.VP16-GFP or VZV.BAC-GFP and at four hpi cells were treated with the specific EGFR inhibitor AG1478 and infection frequencies determined at different hpi by flow cytometry." (PMID 32547533, 2020). "These novel findings contribute to our understanding of how EGFR and its canonical downstream effectors (PLC-γ1 and Akt) are manipulated during BoHV-1 productive infection in diverse cell types." (PMID 32846937, 2020). "Since UL138 acts to maintain EGFR surface levels and MEK/ERK signaling, a feed-forward loop of EGR1 expression, UL138 expression, and EGFR surface levels is established during infection." (PMID 32759334, 2020). "Oral epithelial cells respond directly to the presence of candidalysin by activating epidermal growth factor receptor (EGFR), a key tyrosine kinase important in cell biology and infection." (PMID 32178483, 2020). "Our results show that the infection-mediated increase in cleaved caspase-9 and caspase-3 levels is overall higher in PBMO, whereas exclusively in CBMO, EGFR inhibition increases the infection-mediated cleavage of both caspases." (PMID 32082070, 2019). "In PBMO, inhibition of EGFR abolished both AREG- and infection-induced increases in intracellular Bcl-2 levels; however, in CBMO, it did only suppress the increase which was mediated by stimulation with AREG." (PMID 32082070, 2019). "In the infection progression of C. albicans SC5314, orf19.1816 (ALS3) plays a significant role in cell adhesion and endocytosis induction by interacting with EGFR, ERBB2 (HER2), CDH1 (E-cadherin), HSP90B1 and TJAP1 (TJP4)." (PMID 30769958, 2019). "EGFR knockdown cells were infected with RSV-GFP and infection was evaluated by viral GFP intensity quantified by ELISA reader 17 h p.i. and by plaque titration 24 h p.i. on Vero cells." (PMID 31381610, 2019).
infection (continued). "Inhibition of EGFR abolished both AREG- and infection-induced increases in pBAD, suggesting that phosphorylation of BAD is induced by EGFR-mediated signaling." (PMID 32082070, 2019). "Here, we studied plasma membrane dynamics of CD151 and EGFR and the HPV16 capsid during the early phase of infection." (PMID 31107240, 2019). "Several secondary L1-specific receptors have been proposed to mediate the infection, such as α-6 integrin, keratinocyte growth factor receptor (KGFR), epidermal growth factor receptor (EGFR) and tetraspanins." (PMID 29346309, 2018). "We also investigated this interaction in hBMECs upon infection with meningitic E. coli K1 strain RS218, and a similar result of increased binding of ACTN4 to EGFR was also observed." (PMID 30687645, 2018). "Following infection with HCMV, EGFR becomes rapidly phosphorylated in monocytes, followed by downstream phosphorylation of Akt." (PMID 29547547, 2018). "Several proteins (bands) were shown to be induced by PCN033 infection, and one at around 100 kDa was identified as ACTN4 (a type of cytoskeleton-associated protein), through mass spectrum (MS) analysis, suggesting that EGFR might recruit additional ACTN4 protein upon PCN033 challenge." (PMID 30687645, 2018). "After pretreating the cells with EGFR inhibitor AG1478, the infection-induced binding of ACTN4 to EGFR decreased, and its binding to intracellular actin was restored to that of the control level." (PMID 30687645, 2018). "For the MaMTH interaction screen, 5xGAL4UAS-luciferase reporter cells were infected with lentiviral vectors expressing the preys at a multiplicity of infection (MOI) of 0.4, selected in puromycin for 3 days, and transfected with EGFR-wildtype (EGFR-WT)." (PMID 27956147, 2017). "Insect cells were infected with a multiplicity of infection (MOI) of 10 of control or EGFR baculovirus for 48 hours with and without additional EGF followed by detection of total and phosphorylated EGFR by Western Blot." (PMID 28586369, 2017). "Depletion of SOCS5 also resulted in increased viral-induction of EGFR phosphorylation, and the changes in EGFR and PI3K again correlated with increased viral HA levels 2 h post-infection." (PMID 28195529, 2017). "Infection with HCMV TB40 and HSV-1 downmodulated the tetraspanins CD81, CD151, and CD9, as well as EGFR." (PMID 29121670, 2017). "In short, ALP as a S. eriocheiris surface protein, is critical for infection and further supports the role of ALP in S. eriocheiris infection by competitive effection of the EGF/EGFR axis of the target cells." (PMID 28184355, 2017). "In contrast, HBD3 expression is NOD1-independent but relied on epidermal growth factor receptor (EGFR)-mediated ERK activation, suggesting distinct temporal functions for the two antimicrobial peptides during infection." (PMID 28272373, 2017). "After inducing EGFR-, Ras-, InR-, Dp110- or TOR-mutant MARCM clones for 2 days, we initiated gut epithelial damage by feeding the flies P.e. for 1 day to generate an infection." (PMID 28485389, 2017). "The interaction of both pUL135 and pUL138 with EGFR is intriguing given the antagonistic relationship between UL135 and UL138 in the context of infection." (PMID 27218650, 2016). "Our data demonstrate that infection with TGEV resulted in increased glucose uptake and augmented expression of EGFR, SGLT1 and GLUT2." (PMID 27851758, 2016). "To determine the contribution of UL135 and UL138 to EGFR trafficking during infection, we compared UL135STOP or UL138STOP infection to WT infection (expanded in 3D and 3E)." (PMID 27218650, 2016). "Taken together, these results indicate that EGFR is involved in the entry of TGEV and the activation of downstream pathways early in the infection process." (PMID 26933809, 2016). "Relative to WT infection, disruption of UL135 increased EGFR surface levels by 29% (p-value ≤ 0.05), while disruption of UL138 decreased EGFR surface levels by 22% (p-value ≤ 0.05)." (PMID 27218650, 2016).
infection (continued). "In the context of infection in endothelial cells, a proposed site of CMV persistence, CMV binding to EGFR and β1 and β2 integrins induces increased EC proliferation, motility and capillary tube formation indicative of an angiogenic response." (PMID 27218650, 2016). "This pathway was significantly modulated by 24 hours after infection with GLV-1h153 in our study, with downregulation of the EGFR receptor, potentially mimicking effects of EGFR inhibitors." (PMID 27119120, 2016). "The oscillation observed between 10 and 30 minutes in WT or UL135STOP infection is a point for further investigation, but may reflect a destabilization of EGFR internalization, rapid recycling back to the cell surface, or rapid trafficking of an internal pool of EGFR." (PMID 27218650, 2016). "Although cyclin D1 is known to be a target gene of EGFR and STAT3, its transcriptional regulation remains elusive after the infection of virus." (PMID 24499623, 2013). "Downstream effectors of EGFR such as PI3K and PKC were also important for RSV endocytosis and infection." (PMID 23593008, 2013). "Infection with MIC1 ko, MIC3 ko or MIC1-3 ko parasites induces a partial decrease in EGFR-Akt activation." (PMID 24367261, 2013). "We found that EGFR phosphorylation was activated by RSV, and that inhibitors such as iressa targeting this receptor blocked endocytosis and infection." (PMID 23593008, 2013). "CHO cells lack EGFR ErbB1, but are readily infected with HPVs, further demonstrating the ability of HPV to utilize multiple routes of infection." (PMID 22346752, 2012). "Both EGFR specific biochemical inhibitors substantially blocked infection by HPV16 (≥50%), while genistein almost completely inhibited infection." (PMID 22346752, 2012). "Specific inhibitors of EGFR and FGFR only partially inhibit infection, whereas genistein (a general tyrosine kinase inhibitor) completely blocked infection of HaCaT cells with HPV16." (PMID 22346752, 2012). "For this purpose, INT-407 cells were pre-treated for 30 min with AG1478 (EGFR inhibitor), AG370 (PDGFR inhibitor), wortmannin (PI3-K inhibitor) or PF-573228 (FAK inhibitor) followed by infection with wt C. jejuni." (PMID 22204307, 2011). "We further demonstrate that one signaling pathway, the epidermal growth factor receptor (EGFR) pathway, is key to controlling these three cellular and morphogenetic events, therefore ensuring gut homeostasis following infection." (PMID 21176204, 2010). "Our data show that activation of MEK downstream of the EGFR is necessary and sufficient for the VGF–mediated cell survival during infection." (PMID 19388902, 2009). "Conversely, although the EGF peptide independently activated EGFR, its treatment upon vΔVGF infection did not achieve full EGFR activation, reducing phosphorylation levels to those similar to the uninfected cells." (PMID 39817770, 2025). "Among these, the EGFR/Ras/MAPK and JAK/STAT signaling pathways play significant roles in promoting ISC proliferation during intestinal renewal and regeneration following tissue damage or infection." (PMID 41431871, 2025). "Given the critical role of EGFR in catalyzing key signaling cascades, these insights necessitate a detailed investigation into VGF-specific mechanisms for EGFR signaling activation and their consequent impacts upon infection." (PMID 39817770, 2025). "Akin to our data, the pharmacological inhibition, knockdown or knockout of host proteins involved in IAV internalization identified by others, such as EGFR or mGluR2, can impair but not abolish infection." (PMID 40623098, 2025). "Despite increased receptor internalization into lysosomal structures during infection, there is no discernible impact on EGFR half-life." (PMID 38856640, 2024). "Collectively, these results indicate that A. fumigatus activates EGFR both during pulmonary infection in immunosuppressed mice and during infection of HSAE cells, but not A549 cells." (PMID 39314401, 2024).
infection (continued). "A limitation of this study is that actual SARS-CoV-2 was not used to study infection patterns following EGFR pathway inhibition." (PMID 39291996, 2024). "Moreover, we also found that the knockout of EGFR or ERBB2 inhibited the internalization and infection of FMDV." (PMID 38512977, 2024). "Collectively, these results indicate that A. fumigatus activates EGFR during both pulmonary infection in immunosuppressed mice and infection of HSAE cells but not A549 cells." (PMID 39475281, 2024). "Our data evidence that the reduction in EGFR levels mainly results from transcriptional downregulation upon infection rather than increased lysosomal degradation." (PMID 38856640, 2024). "Although macrophages are known to express EGFR, exposure of these cells to gefitinib did not significantly alter their capacity to kill A. fumigatus after 8 and 16 h of infection." (PMID 39314401, 2024). "Rac1 activity acts dominantly in RABV entry but not considerably in attachment or the later infection period, along with upstream factors including EGFR, PI3K, and Akt, which indicated that halting EGFR-PI3K-Akt-Rac1 possibly influenced mostly on viral entry." (PMID 38809020, 2024). "TOB1-knockout inhibited the infection of FMDV, presumably through the EGFR/ERBB2 signaling pathway." (PMID 38512977, 2024). "We discovered infection-induced hepatic expression of EGF and its receptor EGFR." (PMID 37696392, 2024). "Pretreatment of HSAEC1-KT cells with 25 μM gefitinib (a potent inhibitor or EGFR signaling), did not alter infection-induced accumulation of HIF1α." (PMID 38902255, 2024). "K8NPs stimulated the late signaling pathway, including JAK1/2, which may be induced by an EGFR- or IFN-γ–mediated pathway, and affected the induction of hBDs, which kills S. aureus and reduces its intracellular infection." (PMID 38004123, 2023). "EGFR protein levels however did not change in response to infection and even declined at 8h p.i., suggesting a partial turnover of EGFR at later time points of infection following EGF-mediated EGFR activation." (PMID 38033162, 2023). "To evaluate whether EGFR modulators are capable of restricting HEV entry in primary cells, we pretreated PHHs with EGFR modulators, followed by HEVcc (p6) infection." (PMID 36745934, 2023). "After activating EGFR, infection with PEDV induced a more noticeable decline in the NHE3 fluorescence recovery rate at 72 h, while inhibiting EGFR activity followed by infection with PEDV relatively upregulated the fluorescence recovery rate of NHE3, and the effect was better at 2 h." (PMID 38029193, 2023). "Infection of hCMEC/D3 with N. meningitidis for 4h did not further increase S1P or EGF mediated phosphorylation of EGFR." (PMID 38033162, 2023). "We found no significant change in the mRNA expression of EGFR in the kidneys following acute or long-term post-infection." (PMID 37626956, 2023). "For all the NAS strains, the p38 inhibitor significantly improved the epithelial cell survival during the infection, but this was not the case for the EGFR or ERK1/2 inhibitor, which highlights that p38 signaling regulates NAC-induced epithelial damage." (PMID 35720274, 2022). "It has been also shown that myricetin can block an HSV infection via gD and negatively regulate the epidermal growth factor receptor (EGFR), phosphatidylinositol-3-kinase (PI3K), and the Protein kinase B (PKB) cell signaling pathway, which can reduce infection and replication of the HSV." (PMID 36145370, 2022). "It has been shown that IFN-γ inhibited EGFR tyrosine phosphorylation, which could inhibit IAV entry and infection." (PMID 35330686, 2022). "Another gene enriched in HCs, epidermal growth factor receptor (EGFR), was found to be highly expressed and was predicted to participate in the PI3K/AKT signaling pathway in 3 m p.i., suggesting an essential role in host defense against the infection." (PMID 35399512, 2022).
infection (continued). "TGEV spike (S) protein can bind to EGFR and activate EGFR under the premise of TGEV binding to APN, leading to cofilin phosphorylation and F-actin polymerization through the PI3K-Rac1/Cdc42-PAK-LIMK pathway early in TGEV infection." (PMID 36298772, 2022). "At the early phase of the infection processes, JEV induced the phosphorylation of EGFR." (PMID 35847084, 2022). "To exclude the possibility that R-613 entry occurred via the wild-type form of EGFR, typically expressed in neural stem cells (NSCs), we exposed human NSCs to R-613, monitored the cultures up to 96 h and found no infection." (PMID 34578259, 2021). "In monocytes, this receptor likely helps determine tropism for blood leukocytes, as B cells and T cells do not express EGFR, correlating with the lack of infection of these cells." (PMID 34025614, 2021). "However, rather than requiring downstream signaling molecules such as PI3K or MAPK, HBV relies on the interaction between EGFR and host cell adaptor molecules regulating its intracellular trafficking (e.g., AP2A1, EPS15) for productive infections." (PMID 35083168, 2021). "This upregulation of LDs following infection was transient, and interestingly, did not follow the well described homeostatic mechanism of LD upregulation, instead being controlled by EGFR." (PMID 34527863, 2021). "To corroborate the ELISA results identifying human EGF in growth media, we determined that HUVEC proliferation in response to Bb infection or VEGF treatment could be blocked by tyrphostin AG1478; a potent and selective EGFR inhibitor." (PMID 32302357, 2020). "Moreover, HCV was shown to activate the EGFR during entry and also specifically through its NS3/4A protease during infection." (PMID 32316635, 2020). "We speculated that DTMUV induced miR-221-3p expression via related molecular pathways during DTMUV infection, and then miR-221-3p targeted SOCS5 and inhibited its expression, which thus might enhance EGFR activity." (PMID 32373087, 2020). "In contrast, brain organoids treated with the EGFR- or PDGFRα-specific siRNA showed no or very low GFP fluorescence during the entire 20-day post-infection period and exhibited substantially higher growth kinetics compared to control siRNA-treated organoids." (PMID 33205055, 2020). "We screened first, second, and third generation epidermal growth factor receptor (EGFR)-inhibitors with different modes of action and the EGFR-blocking monoclonal antibody cetuximab in a 3D cell culture infection model with primary human keratinocytes and cowpox virus (CPXV) for antiviral activity." (PMID 33198108, 2020). "In oral epithelial cells, C. albicans has been shown to interact with host epidermal growth factor receptor (EGFR) and human epidermal growth factor receptor 2 (Her2) to induce NF-κB pathway activation, especially during the first two hours post- infection (hpi)." (PMID 32887412, 2020). "Steady-state EGFR protein levels were not affected at 24 and 36 h post-infection (hpi), but after infection for 48 h they were decreased to approximately 20% relative to the uninfected control." (PMID 32846937, 2020). "EGFR inhibition in mice results in reduced fungal load and no adverse effects following infection, which likely reflect the documented co-receptor functions of EGFR40." (PMID 31127085, 2019). "For example, EGF increases the infection rate of ADAM17-depleted cells, EGF increases the proximity between L1 and CD151 after ADAM17 knockdown, and ADAM17 knockdown diminishes the overlap between L1 and EGFR." (PMID 31107240, 2019). "Next, to examine if inhibition of EGFR activity could overcome JQ1 resistance in HCC cells, we knocked down EGFR by lentiviral vector-based shRNA infection." (PMID 30770740, 2019). "EGFR is a proviral factor in HPV16 entry (A) and soluble EGF relieves the effect of ADAM17 depletion on the phosphorylation status of ERK1/2 (B, C), HPV16 PsVs infection rate (D) and HPV16-CD151 proximity (E, F)." (PMID 31107240, 2019).